RB1 (RB transcriptional corepressor 1)
Diseases named in the same sentence as RB1 in open-access papers (continued):
Sharing a sentence is not in itself a finding about the gene and the disease.
prostate carcinoma (continued). "Indeed, we observed that homozygous loss of RB1 correlates with higher expression of ACSL4 in the data sets of metastatic castration-resistant prostate cancer." (PMID 36928314, 2023). "However, mutational frequencies vary between tumor types, with bladder cancer and sarcoma samples having the highest proportion of Rb1 mutations (20–25%), followed by prostate cancer, melanoma, and liver and brain cancer (10–15%)." (PMID 35267571, 2022). "Interestingly, the Aurora A inhibitor that targets RB1 loss in a synthetic lethal manner synergized with thymoquinone in prostate cancer cells doubly deficient of RB1 and SUCLA2." (PMID 34359636, 2021). "RB1 loss is associated with tumor progression in both breast and prostate cancers." (PMID 32819446, 2020). "Also, RB1 loss in prostate cancer samples was found to be associated with the transition to the incurable castration-resistant status and poor clinical outcome." (PMID 26160835, 2015). "Moreover, the restoration of wild-type RB1 in RB1-deficient prostate cancer cells promoted apoptosis after radiation or ceramide treatment." (PMID 26160835, 2015). "The loss of pRB expression may also be the result of mutation or microdeletion of the RB1 promoter region, as described in hereditary retinoblastoma and prostate cancer." (PMID 12556968, 2003). "Prostate cancer patients with RB1 loss may be predisposed to CDK4/6 inhibitor resistance." (PMID 40075623, 2025). "Likewise, identification of positive regulators of autophagy overexpressed in NKX3-1-loss and RB1-loss prostate cancer may be effective targets for slowing the aggressiveness of both subtypes." (PMID 38751776, 2024). "Consequently, Rb1 loss in prostate cancer lead to EZH2 and Sox2 increase and gene expression widespread changes that leads toward a stem cell-like state that would facilitate the onset of metastasis, neuroendocrine transdifferentiation, and the acquisition of ADT resistance." (PMID 29888169, 2018). "Similarly, palbociclib has proven activity in Rb1-deficient prostate cancer cells and hepatocellular carcinoma cells in vitro, in which some activity in Rb1-deficient cells may be compensated by related proteins such as p107." (PMID 28903422, 2017). "Collectively, these results demonstrate that the RB1/E2F1 axis mediates the enhanced expression of CDRs in advanced prostate cancer." (PMID 41492471, 2026). "Studies have shown that in the presence of high levels of androgens, AR activity can enhance the Rb1 tumor-suppressor function and downregulate c-myc tumors, leading to suppressed growth in prostate cancer cell lines." (PMID 40075623, 2025).
prostate carcinoma (continued). "Research on prostate cancer has utilized mouse and human models with RB1 deletion, demonstrating that this deletion encourages lineage plasticity, resulting in a histological shift from prostate ADC to NE (small cell) variants." (PMID 40507907, 2025). "This cluster included signatures of loss of function of the tumor suppressors RB1 and PTEN, which have been associated with aggressive disease across many solid tumors including prostate cancer." (PMID 39985777, 2025). "We screened a panel of prostate cancer models and found that responses to BCL-XL inhibition were associated with RB1 loss." (PMID 40436896, 2025). "RB1 was related to many kinds of cancer such as prostate cancer, small cell lung cancer and hepatocellular carcinoma." (PMID 38711596, 2024). "For example, co-loss of RB1 and BRCA is associated with shorter survival in breast and prostate cancer, possibly due to lineage switching and resistance to hormonal therapy." (PMID 38837893, 2024). "Taken together, these findings collectively emphasize the therapeutic potential of targeting DDR pathways, especially in the context of BRCA2 and RB1 co-deletion, to combat the progression of castration-resistant prostate cancer." (PMID 38672640, 2024). "Recent work has shown that NKX3-1 and RB1 copy number losses are among the first alterations to occur in the evolution of prostate cancer." (PMID 38751776, 2024). "The co-deletion of BRCA2 and RB1 emerged as an independent genomic driver of castration-resistant prostate cancer (CRPC), contributing to an aggressive phenotype characterized by epithelial-to-mesenchymal transition (EMT)." (PMID 38672640, 2024). "The Pten−/−; Rb1−/− prostate cancer cells closely resemble the genetic makeup of metastatic prostate cancer cells and were therefore used to emulate our previous findings in patients with high PSA BCR28,29." (PMID 38654015, 2024). "Intriguingly, the data suggest that the genomic background of prostate cancer cells influences the RB1-E2F transcriptional repression program, with implications for tumor behavior." (PMID 38672640, 2024).
prostate carcinoma (continued). "PTEN and RB1 are frequently codeleted in late-stage human prostate cancer, including castration-resistant prostate adenocarcinoma and treatment-emergent neuroendocrine prostate cancer." (PMID 36928314, 2023). "Co-deletion of RB1 and RNASEH2B was associated with PARPi resistance in prostate cancer cell lines due in part to E2F1-induced BRCA2 expression, however, inhibition of ATR was able to overcome this resistance via disruption of E2F1-induced BRCA2 expression." (PMID 37430137, 2023). "Through the analysis of the GRASSO prostate cancer database, we found that the expression of RACGAP1 was significantly increased in patients with PTEN, RB1, and E2F1 gene mutations, suggesting that E2F1 was related to RACGAP1." (PMID 37196108, 2023). "We found that RB1 is deleted in 10% of prostate cancers and intriguingly, that expression of AURKB is negatively correlated with RB1 in prostate cancer." (PMID 35853811, 2022). "The functional role of RB1 alteration in NEPC transdifferentiation has been verified in experimental models of prostate cancer, but the potential role of the other paralogues has not been assessed." (PMID 35368709, 2022).
prostate carcinoma (continued). "Surprisingly, particularly in prostate cancers, SUCLA2 gene deletion was found to take place upon RB1 loss with near to 100% prevalence." (PMID 34359636, 2021). "Homozygous deletion of RB1 is estimated to occur in more than 30% of advanced prostate cancer cases." (PMID 34359636, 2021). "The RB1 gene is involved in transcriptional regulation of mitotic checkpoint genes and also contributes to prostate cancer progression through modulation of androgen signaling." (PMID 33299560, 2020). "In the context of bladder and prostate cancer there is a frequent focal event that is focused over the RB1 gene." (PMID 32242058, 2020). "In this study, we found that patients with prostate cancer whose expressions of RB1 were below median significantly developed CRPC faster compared to patients with expressions higher than the median." (PMID 33299560, 2020). "Defects in the RB1 tumour suppressor are one of the more common driver alterations in prostate cancer progression and Skp2 was shown to be required for RB1 loss initiated pituitary tumorigenesis." (PMID 30885218, 2019). "RB1 depletion conferred increased radiosensitivity in BC and prostate cancer by altering DNA damage repair, thereby inducing apoptosis." (PMID 31591311, 2019). "In general, according to cancer genome studies, RB1 was genetically inactivated in about 22% of patients with prostate cancer." (PMID 27283490, 2017). "A previous study identified the retinoblastoma (RB1) tumor suppressor as a regulator of prostate cancer progression in a sub-set of CRPC cases." (PMID 25575823, 2015). "Indeed, a higher frequency of RB1 mRNA downregulation was observed in recurrent prostate cancers from patients who had undergone combined androgen blockade with respect to cancers from untreated patients, suggesting that RB1 inactivation might be associated with hormone treatment resistance." (PMID 26160835, 2015). "DU145 cells have genetic mutations in two commonly mutated tumor suppressor genes, RB1 and CDKN2A, which likely contribute to the transformation of this prostate cancer cell line." (PMID 25030902, 2014). "Prostate tissue from 43 patients with prostate cancers and ten with benign prostatic hypertrophy (BPH) were studied for loss of heterozygosity of the RB1 gene." (PMID 7526887, 1994). "Additionally, CDRs represent the prostate cancer-specific downstream effectors of the RB1/E2F axis, making them ideal therapeutic targets for prostate cancer in the context of cell cycle control." (PMID 41492471, 2026).
prostate carcinoma (continued). "Together, our data highlight a critical role for EZH2 in maintaining phenotypic plasticity in prostate cancer models involving Rb1 deletion and suggest that its inhibition may restore chromatin dynamics that constrain lineage infidelity." (PMID 40832297, 2025). "Further influence from the tumor microenvironment, metastatic site, or therapeutic pressure may have also played key roles in the transition from AMPC to NEPC in our case, and this places further emphasis on RB1 function on prostate cancer progression." (PMID 39349591, 2024). "While prior research has shed light on the impact of RB1 inactivation on prostate cancer progression and lineage plasticity, there still remains a critical need to comprehensively understand the underlying mechanisms and identify therapeutic vulnerabilities in RB1-deficient CRPC." (PMID 38672640, 2024). "Notably, a parallel investigation in prostate cancer patients underscored the significance of BRCA2 germline mutations, particularly when associated with RB1 heterozygous deletion." (PMID 38672640, 2024). "MT1M loss was a top ProstaMine hit in both NKX3-1-loss and RB1-loss prostate cancer and has not been reported as a factor involved in PCa progression." (PMID 38751776, 2024). "Furthermore, FOXO1, LATS2, and RB1 have been shown to act as tumor suppressor genes in various prostate cancer models." (PMID 38658552, 2024). "Given that DACH1 and RB1 deletion may co-occur in prostate cancer, we sought to determine the functional significance of DACH1 gene deletion, independently of RB1, in the onset and progression of PCa, using a murine model." (PMID 37095257, 2023).